PIK3CA (phosphatidylinositol-4,5-bisphosphate 3-kinase catalytic subunit alpha)
Diseases named in the same sentence as PIK3CA in open-access papers (continued):
Sharing a sentence is not in itself a finding about the gene and the disease.
breast cancer (continued). "However, one contrary example was also observed with predicted PIK3CA mutations in breast cancer." (PMID 29485617, 2018). "Moreover, PIK3CA mutations represent one of the most common molecular aberrations in breast cancer." (PMID 30235292, 2018). "Indeed, preclinical and clinical data support the argument that patients harboring these mutations could potentially benefit from specific therapeutic trials, such as BOLERO-1 and BOLERO-3 trials in breast cancer patients with PIK3CA mutations." (PMID 28404952, 2017). "However, in breast cancers (see Methods for breast cancer subtypes analyzed), mutations in PIK3CA showed a significant tendency to be clonal, i.e. to be present in all tumour cells (P < 0.001), indicative of PIK3CA mutation being an early event in the evolution of this tumour type." (PMID 29170395, 2017). "In breast cancer this amplification may coexists with an activating mutation of the PIK3CA gene." (PMID 26560478, 2015). "The relationship between PIK3CA mutation and outcome of ER positive breast cancer remains unclear." (PMID 25816324, 2015). "For example, recent studies have shown that PIK3CA mutations are associated with different outcomes in breast cancer depending on whether the tumor is estrogen receptor positive or negative, and whether HER2 is over-expressed or amplified compared to HER2-normal." (PMID 24777052, 2014). "Another PI3Kα-targeted PROTAC, ZM-PI05, degrades both PI3Kα subunits (p110α and p85) and shows a lower IC50 than alpelisib in inhibiting proliferation of PIK3CA-mutant breast cancer cell lines." (PMID 41272322, 2026). "The AKT inhibitor capivasertib is approved in combination with fulvestrant for PIK3CA/AKT1/PTEN-altered advanced breast cancer following results from the CAPItello-291 trial." (PMID 41201834, 2026). "SOLAR‐1 trial showed that fulvestrant plus alpelisib had statistically significant and PFS benefits on PIK3CA‐mutation, hormone receptor‐positive, HER2(−) advanced breast cancer." (PMID 41510186, 2026). "Among molecularly stratified subtypes, approximately 70 % of breast cancer patients are HR+/HER2-, of whom 40 % harbor PIK3CA mutations." (PMID 41496420, 2026). "Recently, inavolisib gained approval from both the U.S. FDA and China's NMPA for PIK3CA-mutated, HR+/HER2− advanced breast cancer following early-stage endocrine therapy relapse." (PMID 41496420, 2026). "Approved agents like alpelisib, combined with fulvestrant, prolong progression-free survival (median 11 vs. 5.7 months) in PIK3CA-mutant breast cancer, while idelalisib–rituximab combinations achieve 83% overall response rates in relapsed CLL." (PMID 40266213, 2025). "In PIK3CA-mutant ER + breast cancer, PI3Kα enhances Wnt activation via INPP4B-mediated GSK3β degradation." (PMID 40804731, 2025). "The authors observed that the sensitivity and specificity of PIK3CA for detecting early-stage breast cancer were 93.3% and 100%, respectively." (PMID 40282403, 2025).
breast cancer (continued). "In the phase 1b clinical trial (NCT03767335), HER2+ advanced breast cancer patients with the PIK3CA mutant received MEN1611 plus only trastuzumab (Group A) or MEN1611 plus trastuzumab and fulvestrant (Group B)." (PMID 40142329, 2025). "Cerebrospinal fluid (CSF) tumor-derived DNA (tDNA) analysis by next-generation sequencing (NGS) was ordered, revealing a gain-of-function variant in PIK3CA, ERBB2 copy number gain, and high aneuploidy, findings consistent with breast cancer brain metastasis." (PMID 41149070, 2025). "Even though PTEN deletion is more correlated to poor outcomes in ER-positive breast cancer, its conjugation with PIK3CA and AKT gene mutations is associated with mammary tumor initiation and proliferation." (PMID 40227634, 2025). "Saudi studies have identified PIK3CA as a key biomarker in breast cancer progression and resistance." (PMID 41523619, 2025). "Alpelisib, a small-molecule inhibitor that targets p110α, is a recommended drug for patients with PIK3CA-mutant advanced breast cancer." (PMID 40991650, 2025). "In 2019, it was approved for clinical use in patients with advanced HR-positive and PIK3CA-mutant breast cancer, in combination with fulvestrant, a selective estrogen receptor degrader." (PMID 40508087, 2025). "The PIK3CA gene, which encodes the PI3K catalytic subunit α isoform (p110α), is mutated in approximately 40% of HR+/HER2- advanced breast cancer patients." (PMID 40535135, 2025). "Between 20-50% of breast cancers exhibit PIK3CA mutations, with the most common being hormone receptor positive or HER2 amplified breast cancer." (PMID 40501689, 2025). "The 2022 ASCO guidelines recommend plasma ctDNA testing for PIK3CA in hormone receptor-positive metastatic breast cancer, given its clinical utility and rapid turnaround." (PMID 40507825, 2025). "Based on its preclinical activity in in-vitro models without causing hyperglycemia, a phase 1 trial (PIKASSO-01) is being conducted in PIK3CA H1047R-mutant advanced breast cancer and other solid tumors." (PMID 41430313, 2025). "The other PI3Kα inhibitor Alpelisib is approved by FDA for use with fulvestrant to treat male and postmenopausal female patients with PIK3CA‐mutated, HR‐positive/HER2‐negative advanced breast cancer that has progressed during or after endocrine therapy." (PMID 40206206, 2025). "The transcriptional landscape in elderly patients with breast cancer is dominated by concomitant somatic mutations, such as ESR1 and PIK3CA." (PMID 40361341, 2025). "Inavolisib, in combination with palbociclib (CDK4/6 inhibitor) and fulvestrant (estrogen-receptor antagonist), is approved for endocrine-resistant, PIK3CA-mutated, HR-positive, HER2-negative breast cancer." (PMID 40576713, 2025). "PIK3CA exerts clinical effects on patients with breast cancer, particularly through the PI3K/AKT/mTOR pathway." (PMID 40142329, 2025).
breast cancer (continued). "Of the various molecular markers and tests designed to help predict the prognosis of breast cancer, the PIK3CA-AKT signaling pathway has been the focus of several studies." (PMID 39929942, 2025). "Research has shown that gain‐of‐function mutations in PIK3CA (the gene encoding p110α, the catalytic subunit) are linked to the overactivation of PI3K, a key mechanism in oncogenesis, especially in breast cancer." (PMID 40206206, 2025). "Therefore, the findings suggest that mutation count could serve as a practical and reliable surrogate marker for PR status prediction in PIK3CA-mutated breast cancer, potentially facilitating more accessible molecular profiling in routine clinical practice without compromising predictive accuracy." (PMID 41425867, 2025). "The SOLAR-1 trial led to the approval of alpelisib plus fulvestrant for patients with PIK3CA-mutated, HR+/HER2− advanced breast cancer." (PMID 41002573, 2025). "When studying the effects of PI3K inhibitors on breast cancer cells, it was determined using qPCR that the resistant cells had over 15 different copies of PIK3CA, compared to 2 in the parental line." (PMID 40564038, 2025). "With advancements in genomic profiling, for instance, the BRCA1/2, HER2, and PIK3CA genes, usually evaluated in breast cancer patients, are now easy to identify." (PMID 39852145, 2025). "Total mutation count shows strong potential as a surrogate biomarker for TMB and a predictive marker for PR status in PIK3CA-mutated IDC, offering a cost-effective genomic tool in personalized breast cancer stratification." (PMID 41425867, 2025). "In HER2-positive, PIK3CA-mutant breast cancer, for instance, HER3 upregulation via HER2-induced phosphorylation is a key compensating mechanism." (PMID 40508087, 2025). "The results of this study indicate that, compared with palbociclib and fulvestrant monotherapy, the addition of inavolisib significantly prolonged PFS and OS in patients with PIK3CA-mutated, HR+/HER2− advanced breast cancer." (PMID 41560743, 2025). "In the context of breast cancer, particularly IDC, PIK3CA mutations are among the most common genetic alterations." (PMID 41425867, 2025). "In the breast cancer liquid biopsies that were positive for CAPItello-defined PIK3CA, AKT1, or PTEN alterations, the most frequently observed ESR1 alterations (> 10.0%) were D538G and Y537S." (PMID 40597213, 2025). "Alpelisib, a selective PI3Kα inhibitor that targets PIK3CA mutations, is approved for hormone receptor–positive, HER2-negative breast cancer." (PMID 41347072, 2025). "The ongoing phase I/II ReDiscover trial (NCT05216432) will further define the potential benefit of RLY-2608 in patients with advanced PIK3CA-mutant solid tumors and breast cancer." (PMID 41430313, 2025). "On the other hand, PIK3CA exhibited the highest mutation rate in the HRG, which aligns with its well-established role in breast cancer pathogenesis, particularly in estrogen-receptor-positive tumors." (PMID 40299459, 2025). "Alpelisib, a selective PIK3CA inhibitor, has been recently approved for treating advanced breast cancer." (PMID 40303291, 2025).
breast cancer (continued). "This suggests that FOXO3 is a pivotal effector of both PI3Kαi and AKTi in PIK3CA altered breast cancer." (PMID 40263319, 2025). "Breast cancer treatment involves targeting key genes involved in cell proliferation, differentiation, and apoptosis, such as PIK3CA, CCND1, HER2, STAT3, WNT1, and KRAS." (PMID 40284420, 2025). "This review aimed to investigate publications and explore therapeutic approaches for PIK3CA-mutant breast cancer." (PMID 40142329, 2025). "Then, we developed a risk prognostic model based on expression levels of PIK3CA, SESN3, ANXA5, MYD88, DPP4, DAXX, and CRIP1 to predict clinical outcomes in patients with breast cancer." (PMID 41357233, 2025). "The most common driver of ER+ breast cancer is PIK3CA, the catalytic subunit of phosphoinositide 3-kinase (PI3K), mutated in 40% of ER+ breast cancers." (PMID 41408399, 2025). "Our current work is consistent with a previous study in ER-positive PIK3CA-mutant breast cancer that identified aberrant mTOR signaling as a dominant mechanism of resistance to PIK3CA-targeted therapy." (PMID 39919177, 2025). "Our study is one of the largest analytical studies of pathogenic alterations in PI3K/AKT pathway genes (PIK3CA, AKT1, AKT2, AKT3, and PTEN) among patients with breast cancer." (PMID 40597213, 2025). "Potent AKT inhibitor; effective in PIK3CA/PTEN‐mutant and trastuzumab‐resistant HER2+ breast cancers; resistance linked to RAS mutations; supports monotherapy and combination." (PMID 40740483, 2025). "HCC1954 (PIK3CA mutant) and SK-BR-3 cells were utilized to test the treatment effects on breast cancers with intact PTEN." (PMID 39920872, 2025). "Recent studies in human breast cancer have shown that KAT7 upregulates phosphoinositide 3-kinase (PIK3CA), leading to activation of the PI3K/AKT signaling pathway, which is known to contribute to cell survival and proliferation." (PMID 41168812, 2025). "The analysis also reveals mutual exclusivity between NF1 shallow deletions and mutations in MAP3K1, PIK3CA, and GATA3, which occur more commonly in luminal breast cancers." (PMID 41226361, 2025). "In HER2-positive breast cancer, the HER2 overexpression causes cellular signaling stress and increases DNA replication errors, resulting in mutations in the PIK3CA and AKT genes of the PI3K/AKT signaling pathway." (PMID 40227634, 2025). "Using this virus to edit breast cancer genes such as Kras and Pik3ca, we generated mammary tumors with high efficiency." (PMID 41000773, 2025). "Regarding alpelisib, the p110α selective inhibitor that has shown such promise in PIK3CA-mutant breast cancer, less research has been conducted in the context of gliomas." (PMID 40508087, 2025). "In breast cancer expressing AKT/PIK3CA pathway alterations, drugs like alpelisib, capivasertib, and inavolisib have recently been approved, demonstrating improved PFS in this specific patient population." (PMID 40989687, 2025). "For instance, both PTEN and PIK3CA, which encodes a catalytic subunit of PI3K, exhibit high mutation frequencies across various neoplasms, including glioblastoma, breast cancer, and gynecologic cancers." (PMID 41130297, 2025). "Loss of both PI-phosphatases increases PI3K/AKT/PRAS40 signaling, breast cancer cell proliferation and colony growth in PIK3CA wild-type (MDA-MB-231, Hs578T) and mutant (T47D) cell lines above that seen with loss of an individual PI-phosphatase." (PMID 41408399, 2025).
breast cancer (continued). "Phase Ib trials are underway to evaluate its efficacy, particularly in PIK3CA‐mutant breast cancer and NSCLC." (PMID 41163374, 2025). "Quantitative analysis of tumor-specific mutations in ctDNA, such as single nucleotide variants in KRAS, NRAS, PIK3CA, BRAF, and EGFR, demonstrated over 80 % concordance with tumor tissue in patients with colorectal, lung, and breast cancers." (PMID 40144458, 2025). "Liver metastases in patients with breast cancer frequently show alterations in the PI3K/AKT/mTOR signaling pathway, with PIK3CA mutations being particularly prominent." (PMID 40075655, 2025). "Some studies have found that the pathological complete response rate of HER2-positive breast cancer patients with wild-type PIK3CA is significantly higher than that of patients with mutant type." (PMID 40472482, 2025). "In MDA-MB-231 breast cancer cells, oncogenes such as PIK3CA, CCND1, HER2, and WNT1 were significantly downregulated, particularly in the FEO-CSNP treatment group, indicating the suppression of proliferative and metastatic signaling pathways." (PMID 40284420, 2025). "This evidence highlights the oncogenic role of KAT7 in enhancing breast cancer radioresistance through transcriptional upregulation of PIK3CA and PI3K/AKT pathway activation, suggesting therapeutic potential in KAT7 inhibition." (PMID 40740483, 2025). "INAVO-121 will compare inavolisib plus fulvestrant with alpelisib plus fulvestrant in a population with PIK3CA-mutated, ER+/HER2− advanced, or relapsed breast cancer progressing after ET plus CDK4/6is (NCT05646862)." (PMID 40244377, 2025). "Its efficacy has been demonstrated in preclinical mouse models and PIK3CA-mutant breast carcinoma patients, suggesting its potential as a targeted therapy for primary breast AS." (PMID 40666093, 2025). "Expression of Pik3ca-mutations in luminal cells (e.g., using promoters MMTV, WAP and Krt8) mostly evoked adenosquamous mammary carcinomas, which exhibited mixed-lineage features highlighted by the presence of KRT14/KRT8 & KRT18 double-positive cancer cells." (PMID 40676433, 2025). "In this scenario, mapping the molecular heterogeneity of patients adds advantages in targeting the PIK3CA gene and represent a step towards personalized treatment in breast cancer and TNBC." (PMID 39369580, 2024). "In conclusion, our study highlights the potential prognostic value of PIK3CA mutations, particularly H1047R, for predicting disease recurrence among women with HR+/HER2- early or locally advanced operable breast cancer." (PMID 39742376, 2024). "Antitumor activity was observed in patients with PIK3CA mutant breast cancer (3 partial response and 3 stable disease of total 6 patients)." (PMID 39070139, 2024). "In the proof-of-concept experiment, ctDNA from the PIK3CA E542K mutant in breast cancer was quantified by detecting a normalized capacitance change rate using a forked-finger gold electrode as the sensing electrode in combination with the ACEK effect." (PMID 38257640, 2024). "Activating mutations of PIK3CA have been detected in ~40% of HR+/HER2- breast cancers, and more than 50% of breast cancer patients harbour oncogenic alterations of at least one member of the PIK3CA pathway." (PMID 39322687, 2024). "Overall, our preclinical data encourage the clinical exploration of this combination for PIK3CA-mutant HR+ metastatic breast cancer patients progressing on standard-of-care therapies." (PMID 39409880, 2024). "Somatic SNVs in PIK3CA are common in human breast cancer, with the majority resulting in kinase gain of function and oncogenicity." (PMID 38610953, 2024).